MLXIPL (MLX interacting protein like)
Diseases named in the same sentence as MLXIPL in open-access papers (continued):
Sharing a sentence is not in itself a finding about the gene and the disease.
tumor (39 papers, 2015 to 2025). "Given the positive correlation between ChREBP protein and tumor malignancy, our findings indicate that the carcinogenic function of ChREBP/MLXIPL arises from the conversion of glucose into fat." (PMID 38933330, 2024). "IHC results revealed an elevation in MLXIPL protein levels in the tumor tissue (unpaired p = 1.03E-2, paired p = 3.27E-2)." (PMID 38698844, 2024). "In summary, the findings suggested that MLXIPL related to tumor-infiltrating CD8+ T cells facilitated a poor prognosis in PCa." (PMID 38698844, 2024). "Then, multivariate analysis revealed that MLXIPL expression, tumor size, and TNM stage (P < 0.05 for all) were independent prognostic factors for DFS." (PMID 33462196, 2021). "Considering that the ChREBP protein is positively correlated with tumor malignancy, these results show that the oncogenic role of ChREBP/MLXIPL results from the conversion of glucose to fat." (PMID 34775964, 2021). "In univariate analysis of OS and DFS, MLXIPL expression, tumor size, and TNM stage emerged as significant independent prognostic factors (P < 0.05 for all)." (PMID 33462196, 2021). "For example, IFN-γ, a cytokine commonly produced by activated T cells, has been shown to influence the expression of various genes within tumor cells and could potentially modulate MLXIPL expression." (PMID 38698844, 2024). "The data from the IHC assay also showed that MLXIPL was elevated in the tumor tissues." (PMID 36809979, 2023). "Among 6 significant hub genes, significantly decreased AGPAT9, AQP7, HMGCS2, KLF15, PPARGC1A mRNA expressions were found in ccRCC tissues compared with adjacent normal tissues, while MLXIPL mRNA expression was significantly elevated in tumor samples compared with normal samples." (PMID 31493764, 2019). "In parallel, increased MLXIPL activity reprograms glucose and glutamine metabolic fluxes into fatty acid and nucleic acid synthesis by increasing the expression of genes involved in lipogenesis, glutamine metabolism and de novo pyrimidine synthesis to support tumor growth." (PMID 38698844, 2024). "Consistently, MLXIPL remained an independent predictor, unaffected by variables such as age, PSA levels, tumor purity, T and N stages, and Gleason score." (PMID 38698844, 2024). "MLX interacting protein like (MLXIPL) is an important regulator of glucolipid metabolism and is involved in tumor progression." (PMID 36809979, 2023). "In contrast, MLXIPL+ macrophages and pDCs were nearly absent in precancerous tissues, but accumulated during tumor initiation and metastasis." (PMID 41246350, 2025). "The abnormal expression of MLXIPL was related to tumor stage and differentiation but was not related to age, sex, or tumor size." (PMID 36809979, 2023).
cancer (34 papers, 2014 to 2026). A tumor composed of atypical neoplastic, often pleomorphic cells that invade other tissues. "Accumulating evidence suggests that MLXIPL has a crucial role in cancer pathology and tumorigenesis." (PMID 38698844, 2024). "It is possible that one or more of these immune mediators directly or indirectly upregulate MLXIPL expression in cancer cells." (PMID 38698844, 2024). "Based on the mRNA and protein level in the six patients used in this study, the expression level of MLXIPL in cancer tissues was generally higher than in normal liver tissues." (PMID 33462196, 2021). "As a promising biological candidate reflecting the microenvironment and cancers, MLXIPL transitivity stimulates aerobic glycolysis by regulating glucose and lipid metabolism hallmark-related genes." (PMID 31493764, 2019). "Using gene expression profiles, we established a gene-signature (CAV1, CD36, MLXIPL, CPT1C, CYP2E1) that strongly associated with epithelial-mesenchymal program across multiple cancers." (PMID 26725848, 2016). "For instance, alterations in hypoxia levels, nutrient availability, or extracellular matrix composition could affect the metabolic state of cancer cells, potentially inducing MLXIPL as part of a broader metabolic reprogramming." (PMID 38698844, 2024).
metabolic disease (25 papers, 2016 to 2025). A congenital disorder (due to inherited enzyme abnormality) or acquired (due to failure of a metabolically important organ) disorder resulting from an abnormal metabolic process. "Based on the pseudo-temporal continuum profile, we identified the TF (ALX4, HINFP, CEBPA, CEBPB, DMBX1, MLXIPL, ONECUT1, and RBPJL) and depicted the regulated kernel genes co-networks, which were subjected to the metabolism disorders." (PMID 33462196, 2021).
infection (7 papers, 2013 to 2023). The state of being infected such as from the introduction of a foreign agent such as serum, vaccine, antigenic substance or organism. "We found that Ad‐H19‐mediated H19 overexpression in hepatocytes increased MLXIPL expression at 3 and 5 days after infection, while silencing H19 significantly inhibited MLXIPL expression in hepatocytes at protein level." (PMID 31809000, 2020).
cardiovascular disease (4 papers, 2021 to 2024). "Other studies carried out in the Chinese population tried to identify an association between different SNVs of the MLXIPL gene, but only reported an association of the rs3812316 with the risk of cardiovascular disease." (PMID 36432414, 2022). "The MLXIPL gene’s function is related to the carbohydrate response element-binding protein, and in particular, to the rs3812316 polymorphism, to blood triglyceride levels, cardiovascular disease, and metabolic alterations." (PMID 38785970, 2024).
MLXIPL also shares sentences with these, for which no sentence is quoted: Hyperinsulinemia (21 papers); liver cancer (13); colorectal cancer (12); type 2 diabetes (12); Glucose intolerance (11); diabetic nephropathy (7); HCMV infection (7); gastric cancer (5); Hepatic fibrosis (4); hepatoblastoma (4); hepatocellular adenoma (4); non-small cell lung carcinoma (4); fructose intolerance (3); Hypoglycemia (3); Impaired glucose tolerance (3); lipid metabolic disorder (3); chronic kidney disease (2); colon (2); glycogenosis (2); leukemia (2); lung adenocarcinoma (2); lung carcinoma (2); non-alcoholic steatohepatitis (2); overnutrition (2); prostate carcinoma (2); renal fibrosis (2); type 1 diabetes (2); acute myeloid leukemia (1); adenoma (1); alcoholic liver diseases (1).
A further 48 diseases each share a sentence with MLXIPL in 1 paper.